VGF (VGF nerve growth factor inducible)
Diseases named in the same sentence as VGF in open-access papers (continued):
Sharing a sentence is not in itself a finding about the gene and the disease.
tumor (29 papers, 2008 to 2025). "RNA-seq identified robust induction of xenobiotic metabolism (CYP1A1, CYP1B1), oxidative/metabolic stress mediators (GDF15, TIPARP), and tumour-associated genes (FOSB, VGF), alongside repression of tumour suppressors (FAT1, LINC00472)." (PMID 41600570, 2025). "Transcriptome analysis revealed associations between VGF and various pathological processes, including malignancies, exosome release, fibrosis, cell cycle disruption, and tumor immune suppression." (PMID 38528565, 2024). "VGF upregulation was associated with higher tumor grade and higher frequency of patient mortality during follow-up (Middle)." (PMID 38528565, 2024). "Knock-down of EIF4E results in suppression of the tumorigenic and angiogenic properties of the FaDu cell line manifested by loss of capacity to grow in soft agar, reduced expression of angiogenic factors (FGF-2 and VGF), and loss of tumor growth in nude mice." (PMID 31010087, 2019). "VGF was significantly positively correlated with activated mast cells and activated CD4 memory T cells, and negatively correlated with Tregs, suggesting that VGF may be linked to a more pro‐inflammatory and less immunosuppressive tumor environment." (PMID 40600620, 2025). "As SOX9 is involved in the pathogenesis and progression of OSCC and the crosstalks between tumor cells and stromal cells, this factor could be one of the stimuli underlying the VGF upregulation in OSCC." (PMID 38528565, 2024). "In the present study, we integrated VGF expression and prognostic values in ACC using TCGA, GTEx, GEPIA, MethSurv databases and R. VGF expression was Increased in tumor tissues compared with that in normal samples." (PMID 40313932, 2025). "The expression levels of VGF across various cancer types, both normal and tumor tissues, are presented in the plot." (PMID 40313932, 2025). "Increased VGF expression is also correlated with tumor status (with tumor vs. tumor free, p < 0.001), residual tumor (R1&R2 VS." (PMID 40313932, 2025). "The statistical analysis confirms that VGF expression is significantly higher in tumor tissues (p < 0.001), suggesting its potential as a biomarker for cancer." (PMID 40313932, 2025). "Colony formation and CCK-8 proliferation assays further supported the role of VGF in promoting tumor proliferation." (PMID 40592939, 2025). "The correlation between VGF expression and immune cell marker indicated a key role for VGF in regulating tumor immunology in ACC." (PMID 40313932, 2025). "Tumor samples generally exhibit higher VGF expression levels, as seen from the spread of the data points." (PMID 40313932, 2025). "A box plot comparing the mRNA expression of VGF between normal adrenal and tumor tissues shows significant upregulation of VGF in tumors." (PMID 40313932, 2025). "The statistical analysis showed significant overexpression of VGF in tumor tissues for most cancer types." (PMID 40313932, 2025). "VGF is the first neuropeptide precursor to be shown to correlate with immune infiltrates, survival prognosis, and tumor progression in ACC." (PMID 40313932, 2025). "The expression of VGF in the tumor immune microenvironment of ACC is negatively correlated with Th1 cells and T cells, providing evidence that high expression of VGF in ACC patients is associated with poor prognosis." (PMID 40313932, 2025). "In multivariate analysis, only VGF expression (HR = 4.052, p = 0.014) and Residual tumor (HR = 5.310, p = 0.033) were identified as independent prognostic factors for ACC." (PMID 40313932, 2025). "Overexpression of VGF significantly exacerbated liver‐metastatic burden after intrasplenic injection of the cancer cells into mice, whereas our Gq inhibitor GQ127 appreciably attenuated the tumor burden promoted by VGF expression." (PMID 39422674, 2024). "It is important to delineate the potential impacts of VGF on the tumor immune microenvironment (TIME) and patient survival." (PMID 38528565, 2024).
tumor (continued). "Knockdown of VGF inhibited tumor progression and reversed the tumor promoting effect of PYK2 overexpression in NSCLC cells." (PMID 38844957, 2024). "VGF expression was opposite to NUMB expression in this tumor cohort, which is compatible with our previous observation (Middle)." (PMID 38528565, 2024). "The values of circRNAs-miR-432-5p-VGF axis in the therapy of neoplasia and psycho-neural pathology deserve comprehensive investigation." (PMID 38528565, 2024). "This work specifies that the paracrine activities of VGF modulate oncogenic potential, tumor microenvironment, and immune responses during OSCC pathogenesis." (PMID 38528565, 2024). "Consistently, the knockdown of VGF remarkably inhibited the growth and tumor weight of UM xenografts." (PMID 39422674, 2024). "Immunohistochemical staining of the tumor sections demonstrated that VGF knockdown and Gαq inhibition decreased the expression of VGF and Ki67 (cell proliferation)." (PMID 39422674, 2024). "In the present study, we report the role of tumor secreted VGF in promoting the growth and liver metastatic colonization of UM, through an autocrine and paracrine loop." (PMID 39422674, 2024). "From the transcriptome of our OSCC tumor cohort, we retrieved 2121 transcripts significantly co-regulated with the VGF transcript, with r > 0.22 or < -0.22, for further analysis." (PMID 38528565, 2024). "A mouse in vitro study demonstrated that the production of VGF can cause the epithelial-mesenchymal transition (EMT), the dispersion of tumor cells, and resistance to EGFR inhibitors." (PMID 37624511, 2023). "Experimental evidences from in vitro models, mouse xenografts and analysis of patient outcomes showed that VGF expression is associated with resistance to EGFR inhibitors and further induces epithelial-mesenchymal transition (EMT) and tumor cell dissemination." (PMID 31682594, 2019). "Furthermore, we aimed to investigate potential variations in the tumor immune microenvironment between ACC patients with elevated levels of VGF and those with low levels." (PMID 40313932, 2025). "This relationship supports the hypothesis that VGF might play a protective role in NB, possibly offering a novel biomarker or therapeutic target for modulating tumor behavior." (PMID 40600620, 2025). "Univariate analysis showed that VGF expression (HR = 4.071, p = 0.002), T stage (HR = 10.286, p < 0.001), M stage (HR = 6.150, p < 0.001), Residual tumor (HR = 12.617, p < 0.001) and pathologic stage (HR = 6.476, p < 0.001) are significantly correlated with OS." (PMID 40313932, 2025). "However, some research suggests that the peptide products of the VGF are generated in human neuroendocrine cells during early development and their production increases in cases of hyperplasia and neoplasia." (PMID 40313932, 2025). "The enrichment of CKB and VGF in Wnt signaling, FoxO signaling, and DNA replication pathways highlights their critical roles in DNA repair mechanisms and cellular stress responses, where genomic instability drives tumor progression." (PMID 40600620, 2025). "Additionally, GSEA analysis suggests that VGF is involved in cytokine receptor interaction and the P13K-Akt signaling pathway, possibly relating to tumor immunity." (PMID 40313932, 2025). "In addition, Hedgehog‐Gli1 mediates an increase in the expression of circ‐0011536 in tumor exosomes, followed by targeting miR‐451a/VGF signaling to promote tumor growth and increase peripheral nerve invasion and remodeling in PDAC." (PMID 39584047, 2024). "Furthermore, we established a liver metastasis model of UM in nude mice, and demonstrated that VGF overexpression conspicuously promoted metastatic tumor burdens in the liver, suggesting that VGF potently drives liver metastatic colonization of UM." (PMID 39422674, 2024).
tumor (continued). "We found that the knockdown of VGF significantly inhibited the growth of both 92‐1 and MP41 cells with Gαq mutation, whereas its impact on MUM2B cells that harbor wild‐type Gαq or non‐tumor cells (ARPE‐19 and HLE‐B3) was comparatively limited." (PMID 39422674, 2024). "Therefore, we identified three SASP-related genes (VGF, IGFBP3, and ANG), established a risk score, and uncovered detrimental and beneficial tumor subtypes based on these genes." (PMID 37624511, 2023). "Moreover, in vivo experiments demonstrated that mice in the METTL3 overexpression group showed an obviously larger tumor size and tumor weight than the control group, while VGF knockdown inhibited METTL3 overexpression-induced tumor progression." (PMID 37742030, 2023). "In addition, at the protein level, FGF18, IL23A, LIF, and VGF stained more deeply in tumor tissues than in normal tissues, while CCL28 and SLIT2 were only deeply stained in normal intestinal mucosal tissues according to the Human Protein Atlas." (PMID 34017356, 2021). "By our QMSP assay for VGF, some methylation values are also seen in matched normal samples, this could be due to field cancerization of the neighboring regions of the tumor lesions." (PMID 24830820, 2014). "Thus, before the methylation screening test of a larger cohort of urine samples for VGF or a panel of methylated genes including VGF, a matched tumor-urine cohort need to be tested." (PMID 24830820, 2014). "However, peptide products of the neurotrophin-inducible gene VGF are produced in human neuroendocrine cells from early development and increase in hyperplasia and neoplasia." (PMID 18328103, 2008). "Further investigation will clarify if the different expression of VGF, in our model, correlates with a different level of communication intervening into the GBM’s TME of patients with long-term and short-term survival, causing an opposed tumor supporting action." (PMID 35884475, 2022). "PPI analysis indicated that the levels of the mRNAs encoding RBPJ, SKP1, CTNNB1, CDH2, SCG2, VGF, and TFF3 were significantly increased in PanNEN tumor tissues compared with the matched paratumor tissues and may be involved in the DNER signaling pathway in PanNENs." (PMID 33329729, 2020). "The immune checkpoint molecule CTLA-4 demonstrated significant positive correlations with HJURP, VGF and COMP expression (p < 0.05), suggesting potential coordinated regulation of immune evasion and tumor progression pathways." (PMID 40592939, 2025). "Changes in protein levels of VGF, p‐CREB, and p‐ERK in xenograft tumor tissues were consistent with the cell experiments in vitro." (PMID 39422674, 2024). "The opposition in VGF and NUMB expression was also noticed in 18/20 tumor types in the TCGA dataset." (PMID 38528565, 2024). "Of course, future studies will be required to better explain these results and to clarify the mechanistic functions of ALPL, GPR68, NETO1, and VGF in the GBM TME and how they can mediate the success of CW application in the tumor resection cavity." (PMID 35884475, 2022). "In vitro and in vivo data showed that H19 overexpression promoted tumor growth and metastasis and revealed that H19 activated PI3K/AKT/CREB signaling and promoted pNEN progression by interacting with VGF (VGF nerve growth factor inducible)." (PMID 34576322, 2021). "At the molecular level, our data identified robust upregulation of VGF in both ALKAL2‐driven NB cell lines and mouse tumours, a finding also noted by Cazes and coworkers." (PMID 33411331, 2021). "In our current study with ALNs we did not demonstrate any significant changes in expression of IL-17 and TGF-β, as well as PD-L1, VGF and IDO, between tumour-free and metastatic ALNs." (PMID 29390966, 2018). "The VEGF expression and MVD were highly correlated in the cancer tissues again suggesting strongly the link between VGF and MVD and the important roles in tumor biological behavior and progression." (PMID 24860830, 2014).
tumor (continued). "A total of 15 genes (AIM1, ARF, CCNA1, MGMT, hMLH1, PGP9.5, S100A2, APC, RAR-β2, ER-α, ER-β, MCAM, VGF, FKBP4 and SSBP2) were analysed for promoter methylation using QMSP in 57 tumour samples, comprising 43 SEs and 14 NSEs, and 23 NT samples." (PMID 22068818, 2012). "Importantly, our study establishes VGF as a potential prognostic biomarker for ACC and highlights its role in tumor progression and immune modulation." (PMID 40313932, 2025). "In addition to the modulation of function and tumor progression in OSCC, the potential consequence of VGF on immune suppression being disclosed was consistent with previous studies." (PMID 38528565, 2024). "The negative correlation between VGF and CASC15 suggests a potential antagonistic relationship worth exploring, as CASC15 has been implicated in cancer progression and may affect tumor growth and metastasis." (PMID 40600620, 2025). "Moreover, mRNA expressions of CA14, RPE65, IGSF1, SLC18 A2 and CPNE6 were significantly lower in PCa samples compared to benign samples, while HJURP, COMP, KRTAP5-1, VGF, SSTR1, LINC01612, NAALADL2-AS2, AMH and ARHGDIG were elevated in tumor samples (p < 0.05)." (PMID 40592939, 2025). "The analysis of the tumor tissue and biopsy from UM patients may provide more evidence for the role of VGF in UM progression, but we did not get enough tumor tissue at the current stage." (PMID 39422674, 2024). "Importantly, the m6A occupancy of VGF in LUAD tissues was increased compared to tumor-adjacent normal tissues." (PMID 37742030, 2023). "No drinking history affects DAPK methylation, and VGF methylation influences tumor grades 1–2." (PMID 36344942, 2022). "Also of note, as a secretory factor, VGF acts on tumor as well as nontumor cells." (PMID 39422674, 2024). "Three novel tumor-derived exosome genes, insulin‐like growth factor binding protein 6 (IGFBP6), VGF (non-acronym), and T-cell Receptor Constant β Chain-1 (TRBC1), which significantly affected the risk score, were also identified." (PMID 36865549, 2023). "By Spearman correlation test, eight genes (AIM1, CCNA1, MCAM, PGP9.5, hMLH1, ARF, VGF and APC) showed to be independent of each other and were selected to be included in a logistic regression model, which predict the probability of tumour." (PMID 22068818, 2012). "MGMT, VGF, CCNA1 and FKBP4 are interesting, as they could be specific for tumours as all of the normal samples showed no methylation, and in addition, hMLH1 that had only one positive in normal." (PMID 22068818, 2012).
cancer (27 papers, 2012 to 2026). A tumor composed of atypical neoplastic, often pleomorphic cells that invade other tissues. "VGF is predominantly known for its role in neuroendocrine regulation but has increasingly been implicated in cancer biology." (PMID 40313932, 2025). "On the other hand, there was a downregulation of TF (coding for iron-binding factor) and VGF, a neuropeptide precursor implicated in cancer progression and metastasis." (PMID 37834191, 2023). "In The Cancer Genome Atlas (TCGA) database, we found MDK is the highest upregulated growth factor in different types of cancer, even higher than that of established growth factors such as VGF, EGF, and TGFB1." (PMID 35487917, 2022). "Nonetheless, the precise role of VGF in angiogenesis and cancer progression remains less characterized." (PMID 25980435, 2015). "VGF is a secreted neuropeptide, recently reported to be methylated in cancer in a “Cancer Methylome” discovery approach by our group." (PMID 24086249, 2013). "From a clinical point of view, our findings suggested that 5-aza-dC treatment is able to restore VGF expression in cancer cell lines and that over-expression of exogenous VGF inhibit colony formation of OC cells." (PMID 24086249, 2013). "We recently reported cancer specific methylation of VGF in two other hormone related cancers (breast and testicular)." (PMID 24086249, 2013). "The neurosecretory protein VGF plays an important role in neurodegenerative and psychiatric diseases, but its role in cancer remains unclear." (PMID 39422674, 2024). "Therefore, our results significantly enhance our understanding of the precise regulation of the VGF expression in cancer." (PMID 37742030, 2023). "Because our IHC analysis suggested a stronger induction of VGF immunoreactivity in the nerves as they come in close contact with cancer cells, we went on to verify whether in vitro contact co‐culture system could recapitulate this pattern of VGF expression." (PMID 30690892, 2019). "VGF-derived peptides exert an extensive array of biological effects in energy metabolism, mood regulation, pain, gastric secretion function, reproduction and, perhaps, cancer." (PMID 28934328, 2017). "VGF and its derived peptides are also believed to play a role in cancer." (PMID 28934328, 2017). "VGF show a significant cancer-specific methylation (P=0.008, by Fisher's exact test)." (PMID 22068818, 2012). "Among four novel methylation markers in OPSCC (AGTR1, CSGALNACT2, GULP1 and VGF), AGTR1 showed a significant correlation with cancer specificity, HPV infection specificity and p16 + /RB- phenotype." (PMID 36344942, 2022). "For example, the VGF nerve growth factor inducible (VGF) plays a role in cell plasticity and induces transcription factor TWIST1, which facilitates EMT in cancer cells." (PMID 33225905, 2020). "We further analyzed the expression behavior of VGF in parental DU145 and LNCaP cells grown under sphere-forming conditions (see S8 Fig for microscope images) that enrich cancer stem cell populations." (PMID 31682594, 2019). "Interestingly, the up‐regulation of VGF in PC12 cells was even higher when they were in direct contact with cancer cells, which could be due to either exposure of PC12 cells to locally higher concentration of soluble paracrine factors or direct cell‐to‐cell communication." (PMID 30690892, 2019). "Both VGF and PGP9.5 methylation showed a cancer specific pattern, with 43% and 85% frequency respectively in tumors, while 0% in normals." (PMID 24086249, 2013). "ESR1, PGP9.5, HIC1 and VGF showed cancer specific methylation pattern in the training set explored, and we chose PGP9.5 and VGF to be further explored in an independent validation set." (PMID 24086249, 2013). "VGF is released from infected cells to induce proliferation, and VAC strains with VGF deletions show selective replication in cancers with an activated EGFR." (PMID 22899907, 2012).
cancer (continued). "Likewise, reverse correlation in VGF expression and IL23R expression was also noted in nearly all malignant tumor types (11/12) in the TCGA database, including those carcinomas in breast and prostate, NSCLC, and CRC." (PMID 38528565, 2024). "Consistently, NET cells in state 1 showed a higher expression of cancer stem cell biomarkers (CD44, VGF, and ID2, etc.)and elevated activities of bile acid‐related metabolism and inflammation, whereas state 2 showed enhanced cell proliferation and downregulated cell junction process." (PMID 34185421, 2021). "There are very limited functional studies that have been performed for VGF and, to our knowledge, no functional studies has been reported for VGF in cancer." (PMID 24086249, 2013). "VGF is a gene recently reported to be methylated in cancer by our group and had never been analysed in TGCT." (PMID 22068818, 2012). "KEGG pathway enrichment analysis of DEGs comparing high- and low-VGF expression groups in the TCGA-PRAD cohort demonstrated significant involvement of key oncogenic pathways, particularly the mTOR signaling pathway and the PD-L1 expression/PD-1 checkpoint pathway in cancer." (PMID 40592939, 2025). "VGF is an important regulator of metabolism and endoplasmic reticulum (ER) stress in neurons and endocrine cells, where it activates pro-survival signaling pathways such as PI3K/AKT/mTOR and MAPK/ERK1/2, but its role in regulation of cancer cells remained unclear for a long time." (PMID 31682594, 2019). "However, the role of VGF in the regulation of cancer cells is still not clear." (PMID 37624511, 2023). "In contrast, the expression of VGF (non-acronymic, the neurosecretory protein, also known as secretogranin VII) was downregulated in high-M1/M2 ratio vs. low-M1/M2 ratio pan-cancers." (PMID 41567365, 2026).